TSPYL2 (TSPY like 2)
Description:
Part of the CASK/TBR1/TSPYL2 transcriptional complex which modulates gene expression in response to neuronal synaptic activity, probably by facilitating nucleosome assembly.
Synonyms: NP79; CDA1; DENTT; TSPX; HRIHFB2216; SE20-4; CTCL; CINAP; SE204
Tractability: PROTAC: UniProt records ubiquitination sites on it; ubiquitination databases record sites on it.
Gene: Protein-coding gene on chromosome X (53,082,326 to 53,088,541, forward strand). Ensembl gene ENSG00000184205.
Subcellular location: Nucleus; Cytoplasm
Pathways (Reactome):
Cellular responses to stimuli: XBP1(S) activates chaperone genes
Gene Ontology:
Molecular function: protein binding; rDNA binding
Biological process: negative regulation of cell growth; negative regulation of DNA replication; regulation of protein kinase activity; negative regulation of cell cycle; regulation of signal transduction; nucleosome assembly
Cellular component: nucleolus; nucleus; chromatin; nucleoplasm; cytoplasm
Homologues: Orthologues: chimpanzee TSPYL2 (99% identical), macaque TSPYL2 (96% identical), rabbit TSPYL2 (79% identical), dog TSPYL2 (78% identical), pig TSPYL2 (77% identical), rat Tspyl2 (72% identical), mouse Tspyl2 (71% identical), guinea pig TSPYL2 (67% identical), zebrafish tspy (17% identical), Caenorhabditis elegans spr-2 (14% identical), Drosophila melanogaster Set (12% identical), Drosophila melanogaster Nap1 (8% identical), and 4 more. Paralogues in human: TSPYL1 (24% identical), TSPYL4 (23% identical), TSPYL6 (22% identical), TSPYL5 (20% identical), SETSIP (16% identical), SET (15% identical), TSPY4 (14% identical), TSPY9 (14% identical), TSPY10 (14% identical), TSPY2 (14% identical), TSPY3 (14% identical), TSPY8 (14% identical), and 6 more.
Diseases named in the same sentence as TSPYL2 in open-access papers:
TSPYL2 is named in the same sentence as 45 diseases in open-access papers, as found by Europe PMC text mining. Sharing a sentence is not in itself a finding about the gene and the disease. The quoted sentences say what the papers report.
lung carcinoma (8 papers, 2007 to 2025). "The TSPYL2 gene is silenced in glioma and malignant lung tissue, and in certain lung cancer cell lines." (PMID 27458158, 2016). "Depletion of TSPYL2 rescues the EMT phenotype of TSPYL1 knockdown in A549 lung carcinoma cells." (PMID 38588050, 2024). "To test this hypothesis, we silenced TSPYL2 in the lung cancer H2228 (female) and A549 (male) cell lines." (PMID 36918555, 2023).
glioma (5 papers, 2011 to 2023). A benign or malignant brain and spinal cord tumor that arises from glial cells (astrocytes, oligodendrocytes, ependymal cells). "TSPYL2 has been found to be mutated in endometrial carcinoma and downregulated in glioma, human and mouse lung primary tumors and hepatocellular carcinoma." (PMID 36918555, 2023). "Testis-specific protein Y-encoded 2 (TSPYL2) was the top-hit gene most negatively correlated with IDH1 expression in the All gliomas and primary GBM analyses." (PMID 35877430, 2022). "In gliomas, some members including TSPYL2 are downregulated due to epigenetic silencing and inhibit tumor growth." (PMID 35877430, 2022). "We next wanted to investigate the transcription factor responsible for TSPYL2 upregulation upon genotoxic stress and we decided to investigate E2F1 involvement because of its role in the DDR and in glioma sexual dimorphism." (PMID 36918555, 2023). "In agreement with the notion that TSPYL2 is a negative cell cycle regulator, TSPYL2 is silenced in glioma tissues, malignant lung tissues and certain lung tumor cell lines." (PMID 21738728, 2011).
prostate carcinoma (5 papers, 2017 to 2025). A carcinoma that arises from epithelial cells of the prostate gland. "Numerous studies have reported that Tspyl2 gene acts as a tumor suppressor gene, and its encoded protein CDA1 is significantly downregulated in various types of tumors, such as glioma, lung cancer, liver cancer, and prostate cancer." (PMID 37391440, 2023).
breast carcinoma (3 papers, 2016 to 2021). "Overexpression of TSPYL2 can inhibit human lung and breast cancer cell lines." (PMID 27458158, 2016).
diabetes (3 papers, 2010 to 2025). "At 20 weeks of diabetes, expression of these genes increased by more than 5-fold (Tspyl2), 10-fold (Tgf-β), 15-fold (Ctgf), compared with age matched non-diabetic animals." (PMID 24710090, 2010).
osteosarcoma (3 papers, 2022 to 2025). A usually aggressive malignant bone-forming mesenchymal neoplasm, predominantly affecting adolescents and young adults. "To extend these findings, we analyzed TSPYL2 protein stability in the osteosarcoma cell lines U2OS (female) and MG-63 (male)." (PMID 36918555, 2023). "Kaplan Meyer curves revealed that low expression of TSPYL2 well correlates with reduced survival in lung adenocarcinoma and osteosarcoma." (PMID 36918555, 2023). "The results of the cell further identified that the expression levels of PREB and STC2 were higher in osteosarcoma cells than in normal osteoblasts, while TSPYL2 and ATP6V0D1 exhibited the opposite results." (PMID 35754801, 2022). "Finally, based on the results of previous screening, four UPRRGs (STC2, PREB, TSPYL2, and ATP6V0D1) were identified to establish a risk model for osteosarcoma via the multivariate Cox regression analysis." (PMID 35754801, 2022). "Finally, four genes (STC2, PREB, TSPYL2, and ATP6V0D1) were screened to construct and validate a risk signature to predict the prognosis of patients with osteosarcoma." (PMID 35754801, 2022). "To deeply investigate TSPYL2 role in the DDR, we performed a time course analysis in the osteosarcoma cell line U2OS in response to 20 μM treatment with etoposide, a topoisomerase II inhibitor." (PMID 36918555, 2023). "Next, to assess the role of UPRRGs in predicting the prognosis of osteosarcoma, we constructed a prognostic signature to predict the survival of osteosarcoma patients via four genes (STC2, PREB, TSPYL2, and ATP6V0D1)." (PMID 35754801, 2022).
renal fibrosis (3 papers, 2021 to 2025). A final common manifestation of a wide variety of chronic kidney diseases characterized by glomerulosclerosis and tubulointerstitial fibrosis. "Studies have suggested that CDA1 (also known as TSPYL2, TSPX, Se20-4, NP79, CINAP, and DENTT) has a synergistic effect with TGF-β, which activates the TGF-β signaling pathway and promotes the occurrence and development of renal fibrosis in DN." (PMID 33997036, 2021).
pancreatic cancer (2 papers, 2023 to 2024). "Seven genes were identified in mass spectrometry and bioinformatic analysis, all significantly downregulated in pancreatic cancer (GEO data, GSE32676), including TSPYL2, TSR1, METAP2, CYR61, EBF2, CIRBP, and TGFBR3." (PMID 38015024, 2024).
atherosclerosis (1 paper, 2019). A disease characterized by the build-up of fatty material and calcium deposition in the arterial wall resulting in partial or complete occlusion of the arterial lumen. "Accordingly, TSPYL2 expression was upregulated in the aorta of a murine diabetic model of atherosclerosis." (PMID 31249597, 2019).
colorectal cancer (1 paper, 2023). A primary or metastatic malignant neoplasm that affects the colon or rectum. "On the contrary, we also found in The Human Protein Atlas database that in renal and colorectal cancer, TSPYL2 expression is associated with unfavorable prognosis, therefore suggesting for this protein tissues and tumors specific functions." (PMID 36918555, 2023). "In addition, The Human protein Atlas reports that TSPYL2 expression can be prognostic for pancreatic, renal and colorectal cancer, with high expression being favorable in the former and unfavorable in the others." (PMID 36918555, 2023).
cyst (1 paper, 2021). A sac-like closed membranous structure that may be empty or contain fluid or amorphous material. "Functional analyses revealed that knockdown of the negative cell cycle regulator testis-specific Y-encoded-like protein 2 (Tspyl2) in SkMCs prevents myotube formation and at the same time abolishes T. gondii bradyzoite and tissue cyst formation." (PMID 34881198, 2021).
developmental delay (1 paper, 2017). "Duplications and deletions involving KDM5C, IQSEC2 and TSPYL2 that do not overlap with HUWE1, have also been shown to cause developmental delay, intellectual disability, behavioral disturbances and/or autistic features." (PMID 28414775, 2017).
neuroblastoma (1 paper, 2019). Neuroblastoma (NB) is the most common solid, extracranial childhood tumor. "Finally, ChIP showed that hemagglutinin-tagged TSPYL2 co-existed with EZH2 in target promoters in neuroblastoma cells." (PMID 30051352, 2019).
osteoarthritis (1 paper, 2023). A noninflammatory degenerative joint disease occurring chiefly in older persons, characterized by degeneration of the articular cartilage, hypertrophy of bone at the margins and changes in the synovial membrane. "We therefore consider these approaches, including the study of osteoarthritis development in surgical and aging models, as the next steps in our quest to understand the role of NDRG2, WSB1, JMJD6, TSPYL2, HMGB2 and PPP1R15A in osteoarthritis and their inner mechanistic links." (PMID 37033917, 2023).
stomach cancer (1 paper, 2024). "The expression of EIF4E, EXOSC1, IARS1, IGFBP1, and SPCS1 was found to be upregulated in stomach cancer cell lines, while TSPYL2 and TUBB2A showed downregulated expression." (PMID 38700505, 2024). "Based on the TCGA cohort, we integrated clinical factors such as age, stage, N stage, SPCS1, IGFBP1 and TSPYL2 to construct a nomogram to enhance survival prediction for patients with stomach cancer." (PMID 38700505, 2024).
thyroid cancer (1 paper, 2025). "TSPYL2 plays an inhibitory role in a variety of cancers, and its reduced expression is associated with multiple lymph node metastases in thyroid cancer tissues." (PMID 40141028, 2025). "Moreover, TSPYL2 may inhibit thyroid cancer progression by modulating SIRT1/AKT signaling." (PMID 40141028, 2025).
ZIKV infection (1 paper, 2023). "TSPYL2 is known as an inhibitor of cell-cycle progression and activation of its expression may be related to cell-cycle arrest associated with ZIKV infection." (PMID 37243147, 2023).
tumor (14 papers, 2011 to 2025). "TSPX (also known as DENTT, CDA1, and TSPYL2) is an X-linked tumor suppressor gene originally identified as a TGF-β responsive member of the TSPY/TSPY-like/SET/NAP-1 superfamily in a human NSCLC cell line." (PMID 39858622, 2025). "The X-linked gene TSPY-Like 2 (TSPYL2) encodes for a putative tumor suppressor protein involved in cell cycle regulation and DNA damage response (DDR) pathways." (PMID 36918555, 2023). "Among the UBE2C protein partners, TSPYL2 (a member of the testis-specific protein Y-encoded) is a tumor suppressor protein which acts in the chromatin remodeling process." (PMID 31067633, 2019). "TSPYL2 inhibits tumor growth and is thought to be associated with DNA damage." (PMID 36246628, 2022). "Accordingly, we found that TSPYL2 expression is significantly reduced in almost all the analyzed cancer tissues, confirming its tumor suppressor role." (PMID 36918555, 2023). "The TSPY homologue on the X chromosome (TSPX, also known as CDA1, DENTT, and TSPYL2) is another tumor suppressor gene located at the Xp11.2 locus." (PMID 30863497, 2019). "Hence, we demonstrate that while TSPYL2 mRNA is induced in all the tested tumor cell lines after DNA damage, TSPYL2 protein stability is increased only in female cancer cells." (PMID 36918555, 2023). "In addition, we demonstrated that TSPYL2 accumulation is required to sustain cell growth arrest after DNA damage, possibly contributing to protect normal and female cancer cells from tumor progression." (PMID 36918555, 2023). "Similarly, in the TCGA data, TSPYL2 mRNA expression was significantly downregulated in GBM compared to non-tumor." (PMID 35877430, 2022). "Using the TNMplot web tool, we also compared TSPYL2 expression level in different normal and tumor tissues and we found that the mRNA of this gene is significantly reduced in almost all the investigated cancer specimens, further confirming a tumor suppressor role for TSPYL2, as previously suggested." (PMID 36918555, 2023). "Conversely, the genes FTH1, SQSTM1, HSPA6, TSPYL2, PHLDA2, ITGAX, and DNAJA4 are expected to act as versatile protein regulators, potentially suppressing tumor cell genetic instability and promoting autophagy, apoptosis, and other forms of cell death." (PMID 40986633, 2025). "TSPYL2, a member of the TSPY-L nucleosome assembly protein-1 superfamily, can exert anti-tumor effects by inhibiting the cell cycle and regulating DNA damage." (PMID 35754801, 2022). "TSPYL2, JAKMIP1, CIT, and TMTC1 were all significantly downregulated in GBM compared to non-tumor samples (p < 0.001)." (PMID 35877430, 2022). "We wondered whether TSPYL2 behaved as a tumor suppressor, but we observed no spontaneous tumor development in our mutant mice and their life span was normal." (PMID 21738728, 2011). "Three tumor suppresser genes, including CYLD, ATM, and TSPYL2, showed a negative correlation with UBE2C in several cancers with a similar moderate to strong negative correlation for them in the following cancers: LUSC, READ, UCEC, OV, and UCS." (PMID 31067633, 2019).
cancer (12 papers, 2011 to 2026). A tumor composed of atypical neoplastic, often pleomorphic cells that invade other tissues. "In accordance with its multiple functions, defects in TSPYL2 have been associated with different diseases, mainly cancer and neurodevelopmental abnormalities." (PMID 41897314, 2026). "Altogether these results indicate that, after etoposide treatment, TSPYL2 loss promotes the proliferation of female cancer cells, where it accumulates, while leaving unaffected that of male cancer cells." (PMID 36918555, 2023). "Differently, for somatic cancers, we found TSPYL2 mutations in 59 out of 2906 (2%) females and 75 out of 4227 (1,8%) males." (PMID 36918555, 2023). "Exploiting the TCGA database to find TSPYL2 mutations in human cancers, we unexpectedly found that this gene is more frequently mutated in female-specific cancers and that gene modifications mostly affect the functional domains of the protein." (PMID 36918555, 2023). "To investigate the mechanisms underlying TSPYL2 accumulation, we evaluated TSPYL2 mRNA in different cancer cell lines before and after etoposide treatment." (PMID 36918555, 2023). "The occurrence of TSPYL2 induction in male cancer cells that lost the Y chromosome suggests that at least one factor implicated in the repression of TSPYL2 accumulation in males may be encoded by this chromosome." (PMID 36918555, 2023). "Indeed, we found that TSPYL2 accumulation, in male cancer cells, is prevented by the Y-encoded protein SRY, which modulates MDM2 protein levels." (PMID 36918555, 2023). "Accordingly, TSPYL2 has been found more frequently mutated in female-specific cancers." (PMID 36918555, 2023). "Even if it is not known if these mutations have loss of function effects on TSPYL2, these results suggest that this protein’s activities may have important roles in preventing somatic and female-specific cancer formation and progression." (PMID 36918555, 2023). "Altogether these results suggest that TSPYL2 could have distinct functions in different tissues and tumors and that deregulation of its expression or mutations could variously impact on survival depending on the cancer type." (PMID 36918555, 2023). "Here, we demonstrate, for the first time, that, after DNA damage, TSPYL2 protein is regulated in a sex-specific manner in cancer cells." (PMID 36918555, 2023). "Accordingly, we found that, after etoposide, TSPYL2 is required to restrict cellular proliferation specifically in female cancer cells, where the protein is induced by DNA damage, suggesting the importance of TSPYL2 upregulation in these events." (PMID 36918555, 2023). "Conversely, in cancer cells, TSPYL2 accumulates only in females or in those male cancer cells that lost the Y-chromosome during the oncogenic process." (PMID 36918555, 2023). "Strikingly, we also found that upon etoposide, TSPYL2 protein is induced in those male cancer cells (e.g. PC3, SW480 and Be2C) that, during the oncogenic process, lost the Y chromosome." (PMID 36918555, 2023). "Differently, in cancer cells, TSPYL2 is regulated in a sex-specific manner and after DNA damage accumulates only in female cells." (PMID 36918555, 2023).